RGS14 (regulator of G protein signaling 14)
Description:
Regulates G protein-coupled receptor signaling cascades. Inhibits signal transduction by increasing the GTPase activity of G protein alpha subunits, thereby driving them into their inactive GDP-bound form. Besides, modulates signal transduction via G protein alpha subunits by functioning as a GDP-dissociation inhibitor (GDI). Has GDI activity on G(i) alpha subunits GNAI1 and GNAI3, but not on GNAI2 and G(o)-alpha subunit GNAO1. Has GAP activity on GNAI0, GNAI2 and GNAI3. May act as a scaffold integrating G protein and Ras/Raf MAPkinase signaling pathways. Inhibits platelet-derived growth factor (PDGF)- stimulated ERK1/ERK2 phosphorylation; a process depending on its interaction with HRAS and that is reversed by G(i) alpha subunit GNAI1. Acts as a positive modulator of microtubule polymerization and spindle organization through a G(i)-alpha-dependent mechanism. Plays a role in cell division. Required for the nerve growth factor (NGF)-mediated neurite outgrowth. Involved in stress resistance. May be involved in visual memory processing capacity and hippocampal-based learning and memory.
Tractability: Small molecule: a structure with a bound ligand is known. Antibody: its Gene Ontology location is reachable by antibodies, with high confidence; UniProt places it where antibodies can reach, with medium confidence. PROTAC: ubiquitination databases record sites on it; its protein half-life has been measured.
Gene: Protein-coding gene on chromosome 5 (177,357,895 to 177,372,598, forward strand). Ensembl gene ENSG00000169220.
Subcellular location: Nucleus; Nucleus, PML body; Cytoplasm; Membrane; Cell membrane; Cytoplasm, cytoskeleton, microtubule organizing center, centrosome; Cytoplasm, cytoskeleton, spindle; Cytoplasm, cytoskeleton, spindle pole; Cell projection, dendrite; Cell projection, dendritic spine; Postsynaptic density
Subcellular location (Human Protein Atlas): Nucleoplasm; Plasma membrane; Vesicles
Pathways (Reactome):
Signal Transduction: G alpha (i) signalling events
Gene Ontology:
Molecular function: GDP-dissociation inhibitor activity; GTPase activator activity; microtubule binding; protein binding; GTPase activity; signaling receptor complex adaptor activity; G-protein alpha-subunit binding; GTPase activating protein binding; GTPase regulator activity; protein kinase binding
Biological process: cell division; spindle organization; chromosome segregation; G protein-coupled receptor signaling pathway; learning; long-term memory; long-term synaptic potentiation; negative regulation of ERK1 and ERK2 cascade; negative regulation of G protein-coupled receptor signaling pathway; negative regulation of MAP kinase activity; negative regulation of synaptic plasticity; nucleocytoplasmic transport; platelet-derived growth factor receptor signaling pathway; positive regulation of neurogenesis; regulation of G protein-coupled receptor signaling pathway; response to oxidative stress; visual learning; zygote asymmetric cell division; modulation of chemical synaptic transmission; signal transduction
Cellular component: centrosome; cytoplasm; plasma membrane; spindle; dendrite; dendritic spine; nuclear body; nucleus; postsynaptic density; spindle pole; glutamatergic synapse; membrane; PML body
Genetic constraint (gnomAD): Loss-of-function variants: 34 observed, 61.39 expected, observed/expected ratio (o/e) 0.55, 90% interval 0.42 to 0.74. The upper end of that interval is the gene's LOEUF score, 0.74, which puts it in group 3 of 6, group 1 being the genes least tolerant of losing a copy. Missense variants: 739 observed, 746.19 expected, observed/expected ratio (o/e) 0.99, 90% interval 0.93 to 1.05. Synonymous variants: 296 observed, 319.24 expected, observed/expected ratio (o/e) 0.93, 90% interval 0.84 to 1.02.
Homologues: Orthologues: chimpanzee RGS14 (99% identical), macaque RGS14 (98% identical), pig RGS14 (91% identical), guinea pig RGS14 (89% identical), rabbit RGS14 (89% identical), mouse Rgs14 (85% identical), rat Rgs14 (84% identical), tropical clawed frog rgs14 (49% identical). Paralogues in human: RGS12 (43% identical), AXIN1 (18% identical), AXIN2 (16% identical), RGS9 (14% identical), RGS10 (13% identical), RGSL1 (13% identical), RGS11 (12% identical), RGS22 (12% identical), RGS6 (11% identical), RGS8 (11% identical), RGS16 (10% identical), RGS18 (10% identical), and 11 more.